XIAP (X-linked inhibitor of apoptosis)
Diseases named in the same sentence as XIAP in open-access papers (continued):
Sharing a sentence is not in itself a finding about the gene and the disease.
tumor (continued). "To explore the prognostic value of survivin and XIAP, we performed univariate and multivariate survival analyses including variables such as age, gender, tumour size, UICC stage as well as survivin and XIAP expression levels according to the IRS." (PMID 28900184, 2017). "XIAP is a legitimate caspase inhibitor and thus efforts have been made to target XIAP-caspase inhibition to promote tumor cell apoptosis." (PMID 28661476, 2017). "Consistent with our in vitro data, targeted knockdown of survivin or XIAP markedly suppressed in vivo tumor growth of both NEC cell lines." (PMID 28039474, 2017). "We found that GSK-3β acts mainly as a tumor promoter in T-ALL by promoting the stabilization of proteins such as MCL-1, c-MYB, and possibly X-linked inhibitor of apoptosis (XIAP)." (PMID 28872614, 2017). "Consistently, a significant decrease in tumor growth was observed in XIAP-depleted ATC xenografts in nude mice." (PMID 29221164, 2017). "XIAP expression in metastatic tissues was also significantly higher than that in primary tumor sites." (PMID 29190902, 2017). "Here we show that XIAP contributes to Cdc42 homeostasis by direct ubiquitination leading to protein degradation thus controlling filopodia dynamics and tumor cell metastases." (PMID 28661476, 2017). "Twenty-two days after injection, we found a remarkable tumor volume decrease in XIAP-shRNA mice compared with the control shRNA mice (651.2±170.5 mm3 vs. 1,894.6±157.1 mm3, P< 0.01)." (PMID 29221164, 2017). "A study shows that high level of XIAP expression correlates with tumor differentiation and significantly lower recurrence-free survival rates and independently predicting the recurrence of non-muscular invasive bladder cancer in a multivariate analysis." (PMID 28057023, 2017). "In summary, the opposing trends of the regression curves for SCCs of the floor of the mouth and of the tongue indicate a slightly different regulatory role of XIAP as a tumour marker." (PMID 28486965, 2017). "While the expression and potential therapeutic role of IAPs has been demonstrated in several tumor entities, the role of survivin and XIAP in the biology of GEP-NEN remains to be elucidated." (PMID 28039474, 2017). "As compared with the control shRNA group, a significant decrease of tumor growth was observed in mouse xenografts with the XIAP-depleted ATC cells." (PMID 29221164, 2017). "Since their identification, many studies in almost every human tumor including endocrine neoplasms demonstrated an overexpression of survivin and XIAP." (PMID 28039474, 2017). "Immunohistochemical analysis showed negative XIAP expression in well-differentiated PTCs and nodular hyperplasia, while XIAP was positively expressed in most tumor tissues of ATC patients (n = 12), with abundant staining in membranous." (PMID 29221164, 2017). "Since our imunohistochemical data revealed first evidence for a biological role of survivin and XIAP in GEP-NEN tumor biology, we next evaluated the expression levels of both IAP members in our recently established NEC cell lines (NEC-DUE1 and NEC-DUE2)." (PMID 28039474, 2017). "The expression of XIAP in tumor specimens of ATC patients was examined by immunohistochemical staining." (PMID 29221164, 2017). "The observation that survivin and XIAP knockdown impairs tumor growth of NEC cell lines tempted us to investigate the growth-inhibitory and pro-apoptotic effects of IAP antagonizing compounds on NEC-DUE cell lines." (PMID 28039474, 2017). "Depletion of XIAP led to an increased protein stability and activity of Cdc42 in normal and tumor cells." (PMID 28661476, 2017). "Both HIF1α and XIAP expression have been correlated with the progression or severity of neoplastic disease." (PMID 28666324, 2017). "The present study is the first to identify that tumor emboli observed in IBC patient tumor tissue express high levels of NFκB and XIAP." (PMID 28460441, 2017).
tumor (continued). "XIAP-deficient cells exhibited comparable results with a significantly reduced tumour volume (Ctrl: 590.8 ± 220.7 mm3 vs. XIAP KD: 107.9 ± 101.8 mm3; p < 0.01) and weight (Ctrl: 0.26 ± 0.11 g vs. XIAP KD: 0.048 ± 0.064 g; p < 0.01)." (PMID 28900184, 2017). "In conclusion, our studies revealed the other side of XIAP in the control of Rho GTPases (especially Rac1 and Cdc42), the prime drivers of tumor cell migration and invasion." (PMID 28661476, 2017). "Together, our results indicate that tumor hypoxia impairs TRAIL efficacy but this limitation can be overcome by combining TRAIL with SMAC mimetics or XIAP-targeting drugs." (PMID 27166192, 2016). "In recent years, XAF1 being a potent antagonist of XIAP, has been studied with interest for its involvement in tumor suppression." (PMID 27097110, 2016). "Inter-molecular interaction between XIAP and Survivin promoted tumor cell invasion in vitro and metastatic dissemination in vivo in murine model of breast cancer and rat insulinoma." (PMID 27340370, 2016). "It is shown that ectopic expression of anti-apoptosis proteins, such as BCL2 and XIAP, confers tumor cells with resistance to apoptosis, leading to an increase of macroscopic metastasis." (PMID 27329720, 2016). "Therapeutically, we provide experimental evidence that combinatorial treatment strategies with TRAIL and SMAC mimetics or XIAP-targeting drugs overcome the apoptosis-hampering conditions imposed by the hypoxic tumor microenvironment." (PMID 27166192, 2016). "In fact, many IAPs such as cIAP1, cIAP2 and XIAP including Survivin have been shown to exist as tumour exosomes in cancer cell lines." (PMID 27340370, 2016). "In summary, we observed marked suppression of tumor growth and metastasis via suppressing NF-κB/XIAP dependent pathways by EF24 both in CCA cells and nude mice." (PMID 27571770, 2016). "Several studies have also focused on manipulating the apoptotic machinery to eradicate tumour-initiating cells, either by intervening in the extrinsic or intrinsic pathways through the use of XIAP inhibitors or down-regulation of cFLIP." (PMID 26934442, 2016). "Here we show that the RING domain of XIAP strongly inhibits the expression of p63α, a known tumor suppressor." (PMID 27447744, 2016). "Using quantitative Western blotting, the expression levels of XIAP and Smac in tumour and matched normal biopsy tissue were determined in all 29 patients." (PMID 26071313, 2015). "Reducing XIAP with siRNA affects viability in several cell lines and can dramatically sensitize tumor cell to TRAIL mediated apoptosis." (PMID 25686839, 2015). "XIAP is the strongest apoptosis-inhibitor in the IAPs family, which is located at Xq25 and is critically involved in the tumor-tolerant radiotherapy and chemotherapy." (PMID 26231038, 2015). "In tumour XIAP expression increased significantly during the course of neoadjuvant radio chemotherapy (p = 0.004662)." (PMID 26071313, 2015). "Over the past decades, growing evidence has shown that XIAP functions to promote the tumor growth and to inhibit the apoptosis in a variety of tumor cells." (PMID 26231038, 2015). "When we examined expression levels in all 29 patients we see that as tumour tissue became more radio chemotherapy resistant, from RCPath A to RCPath C, XIAP levels significantly increased (p = 0.025)." (PMID 26071313, 2015). "Survivin is known to promote tumor cell invasion (in vitro) and metastasis (in vivo), in cooperation with XIAP, another IAP family member." (PMID 25473903, 2015). "XIAP genes are expressed in most tumor cell lines, and its expression is closely related to tumor progression, recurrence, prognosis, and drug resistance to chemotherapy." (PMID 25951128, 2015). "In RCPath C patients XIAP protein levels were significantly raised in the tumour tissue compared to the matched normal tissue (p = 0.007)." (PMID 26071313, 2015).
tumor (continued). "Levels of XIAP in both normal and tumour tissue were significantly increased in post treatment surgical resection tissue, when compared to pretreatment biopsy tissue." (PMID 26071313, 2015). "Previous studies in our laboratory have shown that destabilization of XIAP/survivin complexes by the TGFβ tumor suppressor signaling leads to inhibition of aberrant cell survival resulting in cell death." (PMID 24173770, 2014). "The levels of XIAP protein assayed in the cytosols from NSCLC tumours (n=28) ranged from 17.6 to 126.6 nmol per mg of total protein." (PMID 24626292, 2014). "This indicates that the apoptosome-generated CS-3 activity can overcome the potential caspase inhibitory effect of XIAP in NSCLC tumours." (PMID 24626292, 2014). "Strikingly, we observed that LCL85 also sensitizes tumor cells to Fas-mediated apoptosis through inducing proteasomal degradation of xIAP." (PMID 24422988, 2014). "X-linked inhibitor of apoptosis (XIAP)-associated factor 1 (XAF1), a XIAP-binding protein, is a tumor suppressor gene." (PMID 24980821, 2014). "In fact, recent studies show that inhibitors of IAP proteins including XIAP can augment both prophylactic and therapeutic antitumor vaccines in vivo and targeting XIAP degradation enhances granzyme and NK cell-induced cytolysis of target tumor cells." (PMID 23341929, 2013). "To further investigate IAP expression in these cells we performed immunoblotting studies of XIAP and survivin protein expression which demonstrated higher levels of both these proteins in the MM tumour cell lines than in primary cells." (PMID 23229133, 2013). "To mimic the effect of combination treatments on XIAP, we transfected the TRAIL-resistant RKO tumor cells with two different XIAP siRNA or control siRNA for 48h and then treated the cells with 200 ng/ml TRAIL for 24h." (PMID 23852390, 2013). "X-linked inhibitor of apoptosis (XIAP)-associated factor 1 (XAF1) is a novel negative regulator of XIAP, which reverses XIAP’s protection role on tumor cells." (PMID 23826230, 2013). "Targeting XIAP through chemotherapeutic drugs modulates its expression and induce apoptotic threshold with the considerable growth reduction in tumor both in vitro and in vivo." (PMID 23613836, 2013). "Several studies have indicated that the transcription factor NF-κB regulates the expression of proteins implicated in facilitating tumor cell survival including Bcl-2, Bcl-xL, c-IAP, survivin and XIAP." (PMID 23437404, 2013). "XIAP expression across different tumour cells was detected by western blotting during the same period." (PMID 24336110, 2013). "The survivin-XIAP complex was also described to enhance XIAP’s capacity to inhibit caspases and to facilitate tumor growth in vivo." (PMID 23936028, 2013). "Embelin is a small molecular inhibitor extracted from Myrsinaceae plants that specifically inhibits XIAP, affecting the proliferation and apoptosis of various types of tumor cells." (PMID 23425971, 2013). "The protein profiles of nine targets, namely IGFBP2, IGF1, SHKBP1, ETS1, IL1α, STX2, MAML3, EGR3 and XIAP were verified as significant contributors to tumor classification." (PMID 24282616, 2013). "The efficacy of NK cell killing was attenuated by upregulation of XIAP to bind caspase-3 in tumor cells to escape apoptosis." (PMID 23634213, 2013). "This is consistent with evidence of processed caspase-3 in tumor cell lines and tumor tissues being offset by the overexpression of XIAP or other IAP family members." (PMID 23408474, 2013). "Embelin is a small molecular inhibitor with specific inhibition of XIAP that affects the proliferation and apoptosis of various tumor cells." (PMID 23425971, 2013). "The combination of HCPT and 5-FU synergistically induces apoptosis, downregulates XIAP and survivin expression and inhibits xenograft tumor growth." (PMID 23721525, 2013).
tumor (continued). "Activation of inappropriate survival mechanisms such as survivin/XIAP and/or inactivation of tumor suppressors (i.e., TGFβ) are involved in promoting cell survival during tumorigenicity and metastasis." (PMID 22672900, 2012). "Embelin is a small-molecule inhibitor extracted from plants of the Myrsinaceae family demonstrating specific inhibition of the X-linked inhibitor of apoptosis protein (XIAP) to affect the proliferation and apoptosis of various types of tumor cells." (PMID 23170120, 2012). "BCL2, Bcl-xL, XIAP and survivin are the most important antiapoptotic members of these two families and are frequently upregulated in human tumours including BCa." (PMID 22797576, 2012). "The most representative NF-κB controlled anti-apoptotic factors are XIAP, cIAP1 and Bcl-xL, which can prevent tumor cell killing effects." (PMID 22438958, 2012). "Two mechanisms contributing to increased survival associated with loss of TGFβ tumor suppressor activity are constitutive AKT activation and survivin/XIAP expression." (PMID 22672900, 2012). "It has been suggested that the interaction of XIAP and survivin promotes the invasion of tumor cells and enhances the metastatic spread in vivo." (PMID 22607367, 2012). "Embelin is a small-molecule inhibitor exhibiting specific inhibition of XIAP that affects the proliferation and apoptosis of various tumor cells." (PMID 23170120, 2012). "XIAP was mainly localized in the cytoplasm of tumor cells, with highly variable positive rate from 1%–85%." (PMID 22403616, 2012). "The cIAP1, cIAP2, and XIAP expression appeared in the form of a cytoplasmic staining pattern, with some nuclear staining in the tumour cells." (PMID 21952624, 2011). "The apoptosis, stem cell and tumor phenotypes of Sept4/ARTS-null mice are suppressed by inactivation of XIAP, demonstrating that ARTS acts mainly by targeting XIAP in vivo." (PMID 21949740, 2011). "The expression of XIAP is significantly correlated with a more aggressive tumor phenotype and decreased OS and DFS." (PMID 22088140, 2011). "Both XIAP and Smac were positive in cytoplasm of tumor cells with strong or moderate intensity, respectively." (PMID 21645409, 2011). "In H460 tumour-bearing mice, XIAP ASOs have also been combined with vinorelbine and γ-irradiation, showing a significant delay in tumour establishment and reduction in tumour volume, respectively." (PMID 19904270, 2010). "In agreement with this, long-term expression of XIAP at concentrations comparable to that in tumour cells (two- to five-fold increase) resulted in little or no resistance towards chemotherapeutic drugs." (PMID 20485285, 2010). "We present a systematic study of siRNA mediated knockdown of XIAP in human tumor cell lines of diverse tissue origin, including cell lines used in previous reports." (PMID 20067634, 2010). "We utilized siRNA to systematically knock down XIAP in ten human tumor cell lines and then monitored both XIAP protein levels and cell viability over time." (PMID 20067634, 2010). "The effect of XIAP depletion on viability of the 10 human tumor cell lines was measured at various time points over 96 hr." (PMID 20067634, 2010). "Our study is a more expansive survey, and supports the idea that XIAP has a critical role in negatively regulating death receptor mediated apoptosis across a wide array of tumor cell lines derived from diverse tissue types." (PMID 20067634, 2010). "XIAP is overexpressed in many tumours in which it confers resistance to chemotherapeutic agents and to TRAIL, an apoptosis-inducing biotherapeutic drug currently tested in various clinical trials." (PMID 20461078, 2010). "Our data suggest that in order to predict the impact of XIAP on chemosusceptibility for a given tumour entity, the expression levels and functional states of all XIAP modulators need to be taken into account." (PMID 20485285, 2010).
tumor (continued). "Most HCC (82,5%, n = 33) displayed XIAP immunoreactivity, whereas 70% (n = 28) of cirrhotic liver tissue (distant from the tumor) expressed XIAP." (PMID 19397802, 2009). "The present immunohistochemical data are consistent with previous reports that XIAP expression was increased in RCC compared with normal kidney and XIAP levels correlated with tumour progression." (PMID 18283311, 2008). "Two separate slides, each containing a core from a different area of the tumor for each patient, were stained with a specific antibody for XIAP." (PMID 17257402, 2007). "Our results showed a strong increase in sensitivity of all three tumor cell-lines to TRAIL treatment up to fourteen fold in XIAP siRNA treated BDE cells." (PMID 16953886, 2006). "Taken together, in order develop anti-neoplastic therapeutic protocols in dog tumors, which represent good clinical models, we investigated the effect of XIAP siRNA on different apoptotic agents in canine tumor cell-lines." (PMID 16953886, 2006). "The inhibitor of apoptosis protein, XIAP, is frequently overexpressed in chemoresistant human tumours." (PMID 15685240, 2005). "Since XIAP expression significantly increased during tumour progression, the expression ratio between XIAP and Smac/DIABLO also markedly increased during progression from early to advanced RCC stages." (PMID 15328523, 2004). "Conflicting observations, however, have been reported between XIAP expression and tumour stage or survival in other tumour types." (PMID 15328523, 2004). "Remarkably, a stage-dependent increase of XIAP expression became evident also on the protein level, thereby further confirming our results on increased XIAP mRNA expression in advanced tumour stages." (PMID 15328523, 2004). "Our results, therefore, demonstrate an increase in antiapoptotic XIAP mRNA and protein expression during tumour progression." (PMID 15328523, 2004). "Western blot analysis confirmed the tumour stage-dependent increase of XIAP expression on the protein level." (PMID 15328523, 2004). "Moreover, IHC staining demonstrates that the expression of BCL‐2, c‐FLIP and XIAP in tumour tissues is also effectively inhibited by imipramine treatment." (PMID 40889216, 2025). "Our findings demonstrated that 9c effectively inhibited tumor malignancy through cell cycle arrest and apoptosis induction with the transcriptional downregulation of anti-apoptotic genes including survivin, Mcl-1, Bcl-2, and XIAP." (PMID 40076615, 2025). "The molecular alterations that take place during tumor progression and result in higher histologic grades could be connected to elevated XIAP expression." (PMID 41253834, 2025). "This tumor-suppressive effect involves inhibition of the NF-κB pathway, as evidenced by reduced nuclear localization of RelA and decreased expression of NF-κB target genes, including cIAP, XIAP, BCL2, and Survivin." (PMID 40562870, 2025). "The combined overexpression of PHH3 and XIAP may therefore represent a dual biological mechanism in tumour progression: PHH3 indicating heightened proliferative drive, and XIAP preventing programmed cell death." (PMID 41253834, 2025). "Mechanistically, the high expression of PD-1 in RT cells could activate pro-survival AKT/mTOR pathways and upregulates the expression of anti-apoptotic proteins (Bcl-2, Mcl-1, and XIAP), thus promoting tumor resilience, under targeted therapies." (PMID 40565027, 2025). "AZD5582 is a small molecule inhibitor targeting XIAP with anti-tumor potential." (PMID 39917292, 2025). "Furthermore, another study demonstrated that the formation of a survivin-XIAP complex within tumor tissue promotes cell motility, contributing to invasion and metastasis." (PMID 41206839, 2025). "Early FDIM was associated with the upregulation of XIAP (X-linked inhibitor of apoptosis protein) and VIM (vimentin) suggesting an increased epithelial-mesenchymal transition (EMT) and apoptosis resistance during tumour initiation." (PMID 40683913, 2025).